CENPF (centromere protein F)
Diseases named in the same sentence as CENPF in open-access papers (continued):
Sharing a sentence is not in itself a finding about the gene and the disease.
tumor (continued). "LPS patients with high CENPF expression might resist anti-tumor immune attack to deteriorate progressively, thus CENPF might be a facilitator of tumor escape (needs to be verified)." (PMID 37108172, 2023). "Firstly, CENPF expression was compared between tumor and normal tissues." (PMID 37108172, 2023). "Furthermore, GSEA analysis and TIMER2.0 were performed to detect the correlation of CENPF with bypass genes and tumor-infiltrating immune cells." (PMID 35154456, 2022). "Correlation analysis showed that CENPF correlated with prognosis and tumor immunity." (PMID 36260870, 2022). "These remind us of the promotion of CENPF in tumor onset and progression." (PMID 35346060, 2022). "In addition to its involvement in tumor cell proliferation, CENPF is also involved in protein degradation in tumor cells." (PMID 36644760, 2022). "Inhibition of CENPF expression could reduce the ability of cell proliferation, migration, and tumor formation in nude mice, and block the cell cycle at G2/M checkpoint." (PMID 33854594, 2021). "The tumor weight and size in the CENPF-KD group were lower than NC group (P<0.001, 0.001)." (PMID 33428600, 2021). "These diverse observations suggest that while CENPF could potentially be a therapeutic target and its role in tumorigenesis may depend on cell type and tumor environment." (PMID 32973403, 2020). "All these suggested that CENPF might also be related to tumor progression to metastasis stage and predict poor prognosis in CC." (PMID 33023625, 2020). "Additionally, we found that the "AC079160.1-miR-539-5p-CENPF" axis was an important regulatory pathway in hypoxia-induced tumor cell stemness." (PMID 33148251, 2020). "Furthermore, CENPF expression was significantly upregulated in the tumor compared with the correspondent controls." (PMID 31527303, 2019). "Upregulation of CENPF protein expression, especially through a gene amplification effect, suggests that high levels of CENPF protein may affect the occurrence of tumors, especially in the early stages of tumor development." (PMID 30778371, 2019). "Many downregulated genes in tumour‐infiltrating peripheral CD8+ T cells are associated with classical IFN responses (IFI6, IFI27, MX1, STAT1, EPSTI1 PARP9, ISG15), cell proliferation (STMN1, CENPF, HELLS, NUSAP1, and DNPH1), and T cell costimulation (CD28, TMIGD2, TNFRSF4, CD27, and TNFRSF18)." (PMID 39350478, 2024). "Therefore, further studies are needed to determine whether CENPF expression affects immune cell infiltration and tumor escape." (PMID 36644760, 2022). "Therefore, CENPF has an important relationship with tumor immunity." (PMID 36260870, 2022). "Moreover, miRNAs can inhibit tumor growth via targeting CENPF." (PMID 35346060, 2022). "Thus, CENPF could serve as a novel target for early diagnosis, tumour stage, and poor outcomes in HBV-HCC." (PMID 34603487, 2021). "In addition, because no somatic point mutations in CDK13, GMNN, or CENPF genes were detected in primary tumor tissues, we think that the oncogenic effects of these genes are mainly due to alterations in gene copy numbers, particularly gene amplification." (PMID 22912832, 2012). "IHC analysis demonstrated that tumour cell markers, including HMGB2, TOP2A, CENPF, and TPX2, were strongly expressed in T1, with HMGB2 showing higher expression than TOP2A." (PMID 40099956, 2025). "A study based on microarray data identified five genes (CDK1, CDC20, CCNB1, CENPF, and MAD2L1) related to the tumor stage, early diagnosis, and poor outcomes." (PMID 40282296, 2025). "We found that CENPF expression was preferentially elevated in CRC tissues compared to adjacent normal tissues, with significantly higher levels in CRC patients with tumor recurrence." (PMID 39922805, 2025).
tumor (continued). "Cluster 13 was exclusively expressed in T1, and the highly expressed markers TOP2A, CENPF, TPX2 and HMGB2 are related to tumour proliferation and malignancy." (PMID 40099956, 2025). "Mechanistically, miR-205-5p downregulation of CENPF amplified the DNA-damaging effects of CDDP, disrupting tumor cell division and proliferation." (PMID 40519684, 2025). "We also established a subcutaneous xenograft model using SiHa cells and found that CENPF knockdown inhibited tumor growth compared to the sh-CENPF group, whereas TBHQ treatment accelerated the tumor growth rate." (PMID 38536579, 2024). "Another study reported a correlation between high expression of the centromere protein F (CENPF) gene and worse survival of DDLPS patients, therefore suggesting CENPF as a malignant indicator of tumor immune infiltration-related survival." (PMID 38254762, 2024). "For instances, differentially methylated m6As in genes such as CENPF, WNT7B and NTSR1 between tumor and normal tissues were hypermethylated in S2 PDAC samples compared to S1 PDAC samples." (PMID 37816727, 2023). "Furthermore, multivariate analysis results indicated that CENPF expression (p = 0.008, HR = 3.752, 95%CI [1.410–9.984]) and new tumor status after treatment (p = 0.023, HR = 4.886, 95%CI [1.249–19.120]) could be regarded as independent prognostic factors for LPS patients." (PMID 37108172, 2023). "A crucial NF-κB regulator, Sam68 (KHDRBS3), was also observed to be elevated in LPS-treated tumor enteroids, along with the genes GEN1, KRIT1, CENPF, and STYK1." (PMID 35884586, 2022). "Knockdown of CENPF and FOXM1 synergistically reduced the proliferation of cancer cells and tumor growth in cell-line-derived xenografts." (PMID 35865168, 2022). "Through scRNA-seq analysis, we identified a cluster of proliferative tumor cells (hepatocytes C4), which had significant levels of KI67, TOP2A, and CENPF." (PMID 35169832, 2022). "Interestingly, while LPS treatment increased the proliferation and expression of the GEN1, KRIT1, CENPF, CPLANE1, STYK1, and KHDRBS3 genes, it decreased the expression of the cancer associated LOC610994, Gpatch4, SLC7A1, ATP13A2, and TEX45 genes in tumor enteroids." (PMID 35884586, 2022). "Consequently, CENPF might be a meaningful biomarker for inferring the prognosis of various cancers, including ACC; Moreover, screening the potential molecular mechanisms of CENPF mediated carcinogenic or anti-tumor signaling pathways may furnish new therapeutic strategies for ACC." (PMID 35123514, 2022). "The expression of CENPF in human ACC samples, GEO, and TCGA databases depicted that CENPF was overtly hyper-expressed in ACC patients and positively correlated with tumor stage." (PMID 35123514, 2022). "By using TCGA and THPA databases, we found five genes, CDK1, CDC20, CCNB1, CENPF, and MAD2L1, that were related to the early diagnosis, tumour stage, and poor outcomes of HBV-HCC." (PMID 34603487, 2021). "We compared the expression of CENPF in LUAD tissues and adjacent non-tumor tissues from the publically online database." (PMID 33390818, 2021). "CENPF knockout significantly inhibited LUAD cell growth, the tumor growth of mice and the expression of ERβ2/5 (P<0.05)." (PMID 33428600, 2021). "To explore the expression and potential role of CENPF in NSCLC (including LUSC and LUAD, separately), we first used the publicly available NSCLC database GEPIA to analyze CENPF mRNA expression between tumor specimens and normal tissues." (PMID 33390818, 2021). "CENPF knockdown can decrease HCC cells ability, form colonies and induce tumor formation in nude mice." (PMID 33390818, 2021). "The expressions of CENPF, ERβ, ERβ1, ERβ2 and ERβ5 in different TNM stages of LUAD and benign primary lesions (BPL) were examined." (PMID 33428600, 2021). "CENPF mRNA expression was significantly elevated in both LUAD and LUSC tissues compared with adjacent non-tumor lung tissues (both P < 0.001)." (PMID 33390818, 2021).
tumor (continued). "It was found that CSCs specifically expressed BIRC5, PTTG1, CENPF and CDKN3 genes and presented a scattering distribution in the bulk tumor tissues, which further verified the relatively rare characteristics of CSCs." (PMID 33162821, 2020). "In the "AC079160.1-has-miR-539-5p-CENPF" axis, AC079160.1 as the ceRNA of has-miR-539-5p participated in the regulation of hypoxia-induced stemness of tumor cells, and affected the progress of LUAD." (PMID 33148251, 2020). "The correlation relationship among the expression levels of CENPF, AC079160.1, miR-539-5p, tumor hypoxia and stemness index was evaluated." (PMID 33148251, 2020). "In conclusion, we found that CENPF, BUB1, BUB1B, KIF23 and TTK were potential key genes involved in regulating hypoxia induced tumor cell stemness." (PMID 33148251, 2020). "Thus, CENPF may function as a tumor promoter during BC progression." (PMID 31632198, 2019). "mRNA patterns of AKT3 suggest essential connections with tumor growth and metastasis, as well as a strong biomarker potential when used with 3 other genes (PTTG1, MND1, CENPF)." (PMID 29321820, 2017). "Silencing CENPF can decrease the ability of HCC cells to proliferate, form colonies and induce tumor formation in nude mice." (PMID 28449718, 2017). "While the initiating cells in recurrent tumors were mainly related to the cell cycle such as MKI67, CKS2, ANLN, CDC20, CDCA8, CENPF, inflammatory signals no longer drive anti-tumor immunity." (PMID 41601649, 2026). "Recently, CENPF has been confirmed to potentially induce CIN in primary breast cancer and participate in the progression of various malignant tumors, making it a key factor in tumor progression and a promising indicator for prognosis." (PMID 39922805, 2025). "Our research finding indicates that there is an apparent upregulation of CENPF in not merely tumor tissues but also cell lines in the carcinomas of the cervix." (PMID 38536579, 2024). "Moreover, correlation analysis by the GEPIA database showed that the mRNA expression of CENPF was evidently overexpressed in ACC tumors compared with that in normal ones (p < 0.001), and was positively correlated with the tumor stage for ACC (p < 0.001)." (PMID 35123514, 2022). "Aberrant activation of CENPF may induce immune dysregulation in DLBCL cells by mediating protein deubiquitination in various immune signaling pathways, which leads to tumor escape of DLBCL, but further experimental validation is still needed." (PMID 36644760, 2022). "Based on downstream analysis, 5 hub genes, including CDK1, CDC20, CCNB1, CENPF, and MAD2L1, that could play a critical role in the early diagnosis, tumour stage, and poor outcomes of HBV-HCC were identified." (PMID 34603487, 2021). "Moreover, ROC curves revealed that CENPF and RACGAP1 exhibited robust discrimination between tumor and normal tissue samples." (PMID 33946043, 2021). "Besides, the expression of CENPF was verified in 13 matched pairs of LUAD tissues and adjacent non-tumor tissues using qRT-PCR." (PMID 33390818, 2021). "Furthermore, CENPF collaborates with FOXM1 to synergistically induce target gene expression and leads to activation of crucial signaling pathways correlated with tumor malignancy." (PMID 33061942, 2020). "Furthermore, the protein level of hnRNPR in the tumor was positively correlated with the expression of CCNB1 and CENPF in clinical samples." (PMID 31527303, 2019). "Interestingly, many of these genes are known to be involved in cell-cycle function (CDK2, CDK6, CCNB1, CEP55, CENPF), transcriptional regulation/tumor suppression (FOXO3, TOP2A), DNA-damage response (ASPM, XRCC4), and tumor progression (CYR61, MACC1, CXCR4)." (PMID 28482906, 2017).
tumor (continued). "Furthermore, the high correlation between copy numbers of CENPF, GMNN, and CDK13 suggests that these three amplified genes utilize and/or share the same tumor-development pathway." (PMID 22912832, 2012). "Moreover, CENPF knockout significantly inhibited LUAD cell growth, the tumor growth of mice." (PMID 39922805, 2025). "To validate FOXM1 and CENPF expression in our cohort of HCC patients, we examined the abundance of mRNA expression of FOXM1 and CENPF in 118 randomly selected pairs of HCC clinical samples (tumor, HCC, and corresponding non-tumorous liver tissues, NT) by real-time RT-PCR analysis." (PMID 35865168, 2022). "Interestingly, when we compared the relative expression of FOXM1 and CENPF in HCC and NT, respectively, we observed that they were positively correlated with each other (r = 0.9258, p < 0.0001), and substantially higher expressions in the tumor samples." (PMID 35865168, 2022). "Regardless of the classification standards (TNM staging/Histology Grade/Vascular invasion) used for analysis, all results revealed that CCNB1, CDC20, and CENPF were already significantly upregulated in the early stages of HCC tumor tissues (T1/G1/Stage I/no vascular invasion)." (PMID 34660300, 2021). "Overall, we identified CENPF, BUB1, BUB1B, KIF23 and TTK as potentially key genes involved in regulating hypoxia-induced tumor cell stemness, and found that AC079160.1-miR-539-5p-CENPF axis may be involved in regulating hypoxia induced tumor cell stemness in LUAD." (PMID 33148251, 2020). "In addition to CENPF down-regulation, IPA analysis suggested many targets involved in tumor-stromal interactions and tumor vascularity by a complex regulatory network that might contribute to the effects of FOXM1 depletion in this cellular model." (PMID 28482906, 2017). "Most of the significantly up-regulated genes were involved in cell cycle/mitosis/cell division (e.g., TTK, CENPF, NEK2), while many of those down-regulated were involved in cell adhesion/cell cycle arrest (e.g., ADRB2, APLP2, MACF1), consistent with a role of these genes in neoplasia development." (PMID 18297132, 2008). "Finally, the five candidate genes DNMT3B, EXO1, MCM10, CENPF and CENPE were combined in a new prognosis tool, Gene Expression Classifier or GEC, that stratifies patients according to the number of activated genes in the corresponding tumour (activation status ON)." (PMID 37592220, 2023). "Furthermore, as the tumor status changed with treatment, the expression levels of these genes changed correspondingly in PBMCs; treated HCC patients without active/residual tumor cells had higher transcript levels of CCNB1, CDC20, and CENPF compared with the other two subgroups of HCC patients." (PMID 34660300, 2021). "To validate the expression of ASMP, BUB1, CENPF, MAD2L1, NCAPG, SGO2, and TOP2A genes in tumor samples and adjoining nontumor samples, we measured their relative mRNA expressions using qPCR." (PMID 36072975, 2022). "MiR-1-3p and CENPF have some correlation with TMB and tumor microenvironment, but not with DNA methylation." (PMID 36260870, 2022). "Seven pairs of tumor and adjacent non-tumorous tissues were selected to verify the expressions of the ZWINT, RRM2, NDC80, KIF4A, CEP55, CENPU, and CENPF genes." (PMID 35028418, 2022).
cancer (95 papers, 2008 to 2026). A tumor composed of atypical neoplastic, often pleomorphic cells that invade other tissues. "Another notable example was CKAP2L, which clusters together with several genes identified from referencing of our immunopeptidomics data, including BIRC5, BRCA2, and CENPF, forming a cluster of genes associated with cell proliferation across cancers." (PMID 41477871, 2026). "Recently, high expression of CENPF has been shown to be associated with the prognosis of various cancers." (PMID 37108172, 2023). "An increasing amount of data reveals that CENPF overexpression is strongly linked to cancer development and prognosis." (PMID 36984548, 2023). "CENPF is a microtubule-binding protein that has been found to be associated with poor prognosis in several types of cancer." (PMID 36849756, 2023). "Clusters 6 and 7 (lymphH6 and lymphH7) exhibited higher levels of pro-survival/cell cycle regulation genes (BIRC5, TOP2A, CENPF) associated with metabolically active cancer pathways." (PMID 34579762, 2021). "Overexpression of Centromere Protein F (CENPF) is associated with tumorigenesis of many human malignant tumors." (PMID 33854594, 2021). "Centromere Protein F (CENPF) also associates with the centromere-kinetochore complex and influences cell proliferation and metastasis in several cancers." (PMID 33344459, 2020). "Centromere Protein F (CENPF) associates with the centromere–kinetochore complex and influences cell proliferation and metastasis in several cancers." (PMID 31632198, 2019). "CENPF was significantly linked with numerous cancers, including HCC." (PMID 39908244, 2025). "In BC tissues, TAP1, PILRA, UBE2C, TMEM51, and MKI67 were significantly upregulated, while the expression levels of SPP1 and CENPF remained unchanged between cancer and adjacent tissues." (PMID 41328437, 2025). "Shared pseudotemporally correlated genes between both integrated datasets included genes associated with proliferation (CENPF and TOP2A), cancer‐associated fibroblasts (DCN and COL1A1) and neurodevelopment (HMGB2 and NPAS3)." (PMID 39836549, 2025). "CENPF is a regulator of cell cycle, differential expression of which has been shown to be related with various cancers." (PMID 37108172, 2023). "The prenylated protein CENPF has been used clinically as a proliferative marker for malignant tumor cell growth." (PMID 37007961, 2023). "CENPF regulates cancer metabolism by regulating pyruvate kinase M2 phosphorylation signal transduction." (PMID 35456460, 2022). "A recent study suggested that overexpressed CENPF exerted as a cancer-driver gene in the formation and development of human cancers." (PMID 35123514, 2022). "CENPF regulates cancer metabolism by modulating the phosphorylation signaling of pyruvate kinase M2." (PMID 35884586, 2022). "Glancing at the expression profiles of CENPF in various cancers, we found that CENPF was overexpressed in ACC and negatively correlated with prognosis." (PMID 35123514, 2022). "FOXM1 has an effect on the biological functions of various cancers through synergistic interactions or transcriptional regulation with CENPF and KIF20A." (PMID 35410446, 2022). "CENPF is a widely studied driver gene in multiple cancers, such as gastric, prostate, breast, and bladder cancer." (PMID 33428592, 2021). "Taken together, our results indicated that CENPF was overexpressed both in vitro and in vivo, which was consistent with the results of previous studies on other cancers 32-36." (PMID 33390818, 2021). "Cluster 0 and 6 were enriched in cells expressing genes related to cell cycle and cancer-associated proliferation (SFRP2, CENPF, TOP2A, UBE2C, CRABP2, MYC)." (PMID 33771987, 2021). "The overexpression of CENPF was tightly connected to the mitosis of cancer cells and the occurrence and development of HCC." (PMID 33854594, 2021). "Less HCC cases had family history of cancer in CENPF high group than those cases in CENPF low group (27.8% vs. 37.4%, P = 0.036)." (PMID 33854594, 2021).